AR (androgen receptor)
Diseases named in the same sentence as AR in open-access papers (continued):
Sharing a sentence is not in itself a finding about the gene and the disease.
prostate carcinoma (continued). "There is a growing body of evidence supporting involvement of the androgen receptor in the progression of hormone-sensitive but also hormone-insensitive prostate cancer." (PMID 29206234, 2017). "Resistance to enzalutamide is also promoted by Snail, which is highly expressed in aggressive prostate cancer, through regulation of AR activity." (PMID 29214142, 2017). "The down regulation of PrKD1 in advanced prostate cancer increases AR activity through at least two distinct mechanisms." (PMID 29108267, 2017). "Prostate cancer depends on AR signaling and has been well studied within the context of this cancer." (PMID 28262798, 2017). "AR overexpression and amplification in prostate cancer cells has been shown to correlate with lower recurrence-free survival rates as well as the transition from hormone sensitive to resistant prostate tumor." (PMID 29206234, 2017). "The androgen receptor (AR) is a major driver of prostate cancer, and increased AR levels and co-activators of the receptor promote the development of prostate cancer." (PMID 28511652, 2017). "Given the potential impact of CNA detection in cfDNA—particularly AR amplification—on therapeutic decision-making in prostate cancer, we next focused on the 76 patients with mCRPC." (PMID 29163793, 2017). "It was reported that the CD133+ cancer-initiating population and CD44+CD24- putative PCSCs in prostate cancer cell lines are AR+." (PMID 28400729, 2017). "Identification of hormone-activated targets of the AR has been fueled by the need for useful markers of prostate cancer progression." (PMID 28394264, 2017). "The PI3K pathway is involved in growth, proliferation, differentiation, and motility, and following the androgen receptor (AR) pathway is the second major driver of prostate cancer growth." (PMID 28444639, 2017). "Given the similarities to breast and prostate cancer, Tangen and colleagues sought to explore the potential for targeting AR-signaling in advanced endometrial cancer." (PMID 28085048, 2017). "The AR and alterations affecting its functional status are therefore likely to play an important role in the development and progression of prostate cancer." (PMID 27902483, 2017). "ARN509 is another second generation of androgen receptor antagonists and mainly used in the treatment of castration resistant prostate cancer." (PMID 28326012, 2017). "In mammalian cells, androgen responds to androgen receptor (AR), which plays a central role in male health and the maintenance or progress of prostatic carcinoma." (PMID 29312607, 2017). "As androgen receptor (AR) signaling is a key pathway for the pathogenesis of prostate cancer, androgen-deprivation therapy remains the principal method for patients with locally advanced and metastatic prostate cancer." (PMID 28423553, 2017). "A related investigation in prostate cancer found that HER2 kinase signaling is required for full activity of AR at low androgen concentration." (PMID 28245550, 2017). "Preclinical studies also established a role of Src in progressive stages of prostate cancer and cross talk between Src and AR signaling." (PMID 28606127, 2017). "This negative regulatory effect of celastrol on microRNAs to induce autophagy was described as well in androgen receptor (AR)-positive prostate cancer cells." (PMID 28664158, 2017). "Pharmacological inhibition of AR signaling represents a compelling and conventional therapeutic strategy for prostate cancer, which leads to a >90% 10-year survival of patients with low-risk, localized prostate cancer." (PMID 29311926, 2017). "Virtually all prostate cancer deaths occur due to obtaining the castration-resistant phenotype after prostate cancer cells escaped from apoptosis and/or growth suppression initially induced by androgen receptor blockade." (PMID 28270124, 2017).
prostate carcinoma (continued). "Previous studies have been conducted to reveal the relationship between androgen receptor CAG polymorphism and risk of prostate cancer, yet the results were elusive and controversial." (PMID 28640128, 2017). "On the other hand, in the therapy of metastatic castration-resistant prostate cancer, androgen action is blocked by androgen deprivation, androgen synthesis inhibitors, and/or the use of androgen receptor (AR) antagonists." (PMID 28168446, 2017). "As noted in multiple review articles, AR activation in castration-resistant prostate cancers appears to occur via at least six potential mechanisms." (PMID 29181019, 2017). "We have demonstrated that PKC may phosphorylate AR at serine 578 and that, in combination with current diagnostic tools, pARS578 protein expression could provide a desperately needed prognostic marker to aid treatment decision-making in prostate cancer patients at diagnosis." (PMID 27902483, 2017). "Second in mutation rate is androgen receptor, the castrate resistant cancer, thought there is less than 10% mutations found in COSMIC reported prostate cancer." (PMID 29206234, 2017). "RNA-seq data show high levels of CEBPB transcripts in multiple prostate tissue cell lines and a marked anti-correlation with AR levels in human prostate cancers (N = 319, P = 8e-18 Pearson correlation)." (PMID 28663546, 2017). "AR antagonists such as flutamide and bicalutamide have been used for prostate cancer for many decades, and new AR antagonists are also under development." (PMID 28475115, 2017). "Androgen receptor (AR) is frequently over-expressed and plays a critical role in the growth and progression of human prostate cancer." (PMID 28151478, 2017). "The androgen-activated androgen receptor (AR) is both the major driver of prostate cancer (CaP) progression and the main target for treatment of metastatic CaP." (PMID 28826481, 2017). "Prostate cancer is the most common cancer in men and targeting androgen receptor (AR) is an effective treatment." (PMID 28415728, 2017). "At the molecular level DR17 targeted simultaneously several molecular signaling axes important in prostate cancer including androgen receptor, mTOR, and PI3K/AKT." (PMID 28350865, 2017). "It is significant that Peptide B-8R kills prostate cancer cells that express AR and sGCα1, since these cancer cells represent the large majority of prostate tumors." (PMID 28859127, 2017). "Prostate stromal cells begin losing AR expression during cancer progression and low AR expression in prostatic stroma is commonly found in patients who have developed resistance to androgen ablation therapy for prostate cancer." (PMID 29145476, 2017). "We analyzed the effect of miR-200a with knockdown and addition of miR-200a in LNCaP cells and showed a positive role of miR-200a in proliferation of AR-positive prostate cancer cells." (PMID 28783103, 2017). "AhR has also been shown to regulate AR signaling which remains functionally important in the development and progression of prostate cancer." (PMID 28671964, 2017). "The androgen receptor (AR) is the main driver of prostate cancer (PC) development and progression, and the primary therapeutic target in PC." (PMID 27903893, 2017). "Part of their findings demonstrate that MageA11 is a co-regulator of the Androgen Receptor (AR) and overexpressed in human prostate cancer samples." (PMID 28542476, 2017). "Therapeutic interventions for advanced prostate cancer (PCa) center on inhibiting androgen receptor (AR) and downstream signaling pathways." (PMID 28077788, 2017). "Taken together these data indicated that prostate cancer tissues under study were indeed in a highly proliferative state and engaged actively in AR signaling pathway." (PMID 28852180, 2017).
prostate carcinoma (continued). "Crosstalk between the AR and PPARγ signaling pathways can also be influenced by the amount of each receptor present within human prostate cancer cells." (PMID 29181019, 2017). "BPA effects on mouse satellite cell differentiation, male rat vascular smooth muscle cells motility, and AR levels and transcriptional activity in human prostate cancer cells have been evaluated." (PMID 28239427, 2017). "Given the fact that AR signaling is also involved in the regulation of ERK1/2 signaling as well as prostate cancer survival, we next sought to determine the inhibitory effects of Exo2 on these cells." (PMID 28830537, 2017). "The activation of androgen receptor (AR) is crucial for PC growth at all stages of the disease and the androgen receptor (AR) signaling is the principal target for prostate cancer treatment." (PMID 28415632, 2017). "The standard treatment for prostate cancer (PCa) is androgen deprivation therapy (ADT) that blocks transcriptional activity of androgen receptor (AR)." (PMID 28036278, 2017). "We chose to use the 22RV1 cell line because it represents the CRPC prostate cancer cells and both full-length AR and ARV7 were expressed endogenously in these cells." (PMID 28903374, 2017). "IGF-2 mRNA was increased in samples of patients with castrate resistant prostate cancer and promoted steroidogenesis resulting in activation of the androgen receptor in vitro." (PMID 28417914, 2017). "Alternative AR mRNA isoforms play a key role in the generation of prostate cancer drug resistance, by providing a mechanism through which prostate cancer cells can grow in limited serum androgen concentrations." (PMID 28382513, 2017). "PCSCs usually have low or undetectable androgen receptor expression that can lead to the failure of androgen deprivation therapy (hormonal therapy), the standard primary treatment for advanced prostate cancer." (PMID 28400729, 2017). "To evaluate the interaction between canine REIC/Dkk-3 and SGTA in the AR signal transduction pathway in canine prostate cancer, we first measured the extent of AR signalling activation by the probasin promoter-driven luciferase reporter assay." (PMID 28599655, 2017). "This work provides evidence that the AR NTD plays an important role in the hormonal progression of prostate cancer and supports the development of AR antagonists that target the AR NTD." (PMID 28306720, 2017). "Here we show that warfarin inhibits the transcriptional activity of the androgen receptor (AR), an important driver of prostate cancer development and progression." (PMID 28099154, 2017). "We investigated the mechanisms of cell cycle inhibition by PHB and how this is modulated by AR in prostate cancer." (PMID 28504694, 2017). "Prostate cancer is the most common male cancer and androgen receptor (AR) is the major driver of the disease." (PMID 28415728, 2017). "Collectively, these data suggest that AR− luminal cells are primarily altered in cell morphology, and share some molecular signatures with prostate cancer cells." (PMID 28112153, 2017). "Studies show that AR expression was 22% higher in the benign prostate and 81% higher in prostate cancer of African-Americans compared to Caucasians." (PMID 28039468, 2017). "In prostate cancer, resistance to the antiandrogen enzalutamide (Enz) can occur through bypass of androgen receptor (AR) blockade by the glucocorticoid receptor (GR)." (PMID 28891793, 2017). "As AR activity remains important in the progression of all stages of prostate cancer, AR continues to be an attractive molecular target of drugs against prostate cancer." (PMID 28570625, 2017).
prostate carcinoma (continued). "This study aimed to assess the effects of REIC/Dkk-3 and SGTA interactions on AR signalling in the canine androgen-independent prostate cancer cell line CHP-1." (PMID 28599655, 2017). "The down regulation of PrKD1, among other mechanisms, contributes to increased AR activity and progression of prostate cancer including castration resistance." (PMID 29108267, 2017). "For example, FOXO1 antagonizes AR activity and its downregulation contributes to increased metastatic activity of prostate cancer cells." (PMID 28055971, 2017). "Treatment-induced neuroendocrine prostate cancer (t-NEPC) is an aggressive subtype of prostate cancer (PCa) that arises as a consequence of rigorous androgen receptor (AR) pathway inhibition (ARPI) therapies." (PMID 29156689, 2017). "Prostate cancer growth is dependent upon androgen receptor (AR) activation, regulated via phosphorylation." (PMID 27902483, 2017). "In early stage prostate cancer, the ligand-activated AR-FL appears to be the form of AR that primarily regulates tumor growth." (PMID 29181019, 2017). "Androgen/AR is the primary contributor to prostate cancer (PCa) progression by regulating Prostate Specific Antigen (PSA) gene transcription." (PMID 28199985, 2017). "It is believed that androgens and the androgen receptor (AR) play significant roles in prostate cancer cell proliferation and invasion." (PMID 28148240, 2017). "In prostate cancer, it was shown that pre-adipocytes promote metastasis by modulating miR-301a/AR/TGF-β1/Smad/MMP9 signals." (PMID 29197379, 2017). "The ongoing efforts to identify better, highly potent and selective compounds that selectively inhibit individual HDMs will be of great help to further delineate the individual roles of members of this enzyme family in AR signaling and prostate cancer." (PMID 28486411, 2017). "AR is a key driver of prostate cancer progression and has been an effective therapeutic target in managing patients with advanced prostate cancer." (PMID 29108267, 2017). "We also report a transcriptional level correlation of AURKA and AR in clinical AR-positive prostate cancer specimens in two independent prostate cancer cohorts." (PMID 29269934, 2017). "The androgen receptor (AR) has long been the primary target for the treatment of prostate cancer (PC)." (PMID 29179452, 2017). "Previous studies have demonstrated that RNF6 as a ubiquitin ligase stabilized AR protein in prostate cancer patients, therefore, we evaluated the effects of RNF6 on the protein expression of ERα." (PMID 28223545, 2017). "The androgen receptor (AR) is highly expressed in primary and metastatic prostate cancer and regulates multiple cellular functions, including proliferation, apoptosis, migration, invasion, and differentiation in all stages of prostate cancer." (PMID 29311926, 2017). "KDM4C co-localizes with the androgen receptor in prostate carcinomas, and knockdown of KDM4C inhibits transcriptional activation and tumor cell proliferation." (PMID 28416760, 2017). "In this review, we explore the relationship between AR signalling in fibroblasts/myofibroblasts and prostate cancer cells in the primary site, and detail the known functions, actions, and mechanisms of fibroblast AR signaling." (PMID 28117763, 2017). "An RT-qPCR analysis of the androgen and anti-androgen regulation of the five candidate STRs was performed given the importance of the AR signaling pathway in prostate cancer progression." (PMID 29203868, 2017). "NCOA1, as the androgen receptor (AR) coactivator, was found to be involved in prostate cancer progression, while NCOA1 knockdown induced a significant decrease in migration and invasion through the upregulation of protein kinase D1 (PRKD1)." (PMID 28060733, 2017). "Let-7c targets the oncogenes such as Ras and Myc and suppresses prostate cancer progression through AR by targeting c-Myc, which is required for AR function." (PMID 28783103, 2017).
prostate carcinoma (continued). "The PlncRNA-1 RNA also acts as a sponge to protect the AR from inhibition by miR-34c and miR-297 in prostate cancer." (PMID 28212533, 2017). "This study has also validated ING3 as a novel prognostic biomarker that can dramatically improve prediction of overall survival in prostate cancer, particularly in cases with low levels of AR." (PMID 28511652, 2017). "Phenothiazine was predicted to interact with the androgen receptor (AR; hsa:367) based on its transcriptional similarity with enzalutamide (D10218), which is marketed for the treatment of prostate cancer and is known to interact with AR." (PMID 28071740, 2017). "Androgen deprivation therapy blocks the androgen receptor from interacting with the signaling molecules; however, this treatment eventually fails because the receptor finds other ways to remain active in prostate cancer." (PMID 28826481, 2017). "The progression to advanced prostate cancer is thought to involve persistence of AR signalling, and prostate cancer treatment is dominated by strategies to control AR activity." (PMID 28701765, 2017). "The androgen/androgen receptor (AR) axis plays crucial roles in both normal prostate function and the development of prostate diseases including prostate cancer." (PMID 28903374, 2017). "To study the peptide activity in hormone-independent, AR-positive prostate cancer cells, we used C81 and CWR-22Rv1 cells." (PMID 28859127, 2017). "Given the pivotal role of AR signalling in prostate cancer development, AR-based therapy was born several decades ago." (PMID 28151478, 2017). "We also included as biological controls several genes known to be important for prostate cancer cell viability: AR, MYC, and KIF11." (PMID 29340039, 2017). "Changing patterns of AR pre-mRNA splicing play a critical role in enabling prostate cancer cells to develop castration resistance." (PMID 28382513, 2017). "All current approved hormonal therapies for prostate cancer aim at preventing activation of AR through chemical or surgical castration and intervention with antiandrogens that competitively bind to the LBD of the receptor." (PMID 28306720, 2017). "Resveratrol suppressed prostate cancer growth via down-regulating the androgen receptor (AR) expression in the TRAMP model of prostate cancer." (PMID 29194365, 2017). "The AR controls prostate cancer development through the regulation of transcription, meaning that identifying both transcriptional targets of the AR and the factors involved will provide opportunities for both cancer detection and therapeutic intervention." (PMID 28701765, 2017). "Beside its repressive role, EZH2 also acts independently of the PRC2 complex and co-activates gene transcription by interacting with transcription factors such as the AR, making it a promising target for prostate cancer treatment." (PMID 28486411, 2017). "In prostate cancer, androgen/androgen receptor (AR) and their downstream targets play key roles in all stages of disease progression." (PMID 28077787, 2017). "This evidence supports the notion that PKD1 is repressed by an AR-induced FGFR/FRS2/MEK/ERK pathway in androgen-sensitive prostate cancer cells." (PMID 28077787, 2017). "Fatty acid synthase (FASN) is an enzyme that controls fatty acid synthesis and has been shown to promote the growth of prostate cancer as a result of AR signaling." (PMID 28208703, 2017). "We further assessed the utility of AF-2-targeting peptidomimetics in blocking AR N-C and AR-cofactor interactions as a potential novel anti-AR strategy for treatment of prostate cancer." (PMID 29050220, 2017). "TIP60/KAT5 is up-regulated in prostate cancer and its impact on nuclear translocation following AR acetylation has been reported." (PMID 28486411, 2017). "In this study, we found that CREB3L4 is essential for prostate cancer cell proliferation, through its modulation of AR activity, which reciprocally, is upstream of CREB3L4 expression (perhaps suggesting some type of positive feedback)." (PMID 28338058, 2017).